ACTL6A (actin like 6A)
Diseases named in the same sentence as ACTL6A in open-access papers (continued):
Sharing a sentence is not in itself a finding about the gene and the disease.
tumor (continued). "To assess the role of ACTL6A in tumor formation, we examined the ability of monolayer cultured wild-type and ACTL6A null cells to form tumors in immune-compromised mice." (PMID 34689163, 2021). "The ACTL6A-overexpressing group had obviously enhanced, whereas knockdown of ACTL6A suppressed tumor growth, both as compared with the vector group." (PMID 33541412, 2021). "ACTL6A and P63 interact physically to synergistically control transcriptional programs that promote tumor proliferation and inhibit differentiation." (PMID 33101383, 2020). "This suggests that ACTL6A plays key roles in embryonic development and is “reactivated” during tumor formation." (PMID 31504061, 2019). "Targeting ACTL6A may therefore reactivate silenced tumor-suppressive gene networks through KLF4, offering a promising epigenetic therapeutic strategy for CRC." (PMID 40877226, 2025). "For example, developing small molecule inhibitors or siRNA-based technologies aimed at ACTL6A could effectively reduce tumor cell proliferation and metastasis." (PMID 40657395, 2025). "Recent studies reveal that aberrant ACTL6A overexpression promotes tumor initiation, progression, and metastasis by orchestrating chromatin remodeling, transcriptional reprogramming, and crosstalk with key signaling pathways (e.g., Hippo/YAP, Notch, and PI3K/AKT)." (PMID 40657395, 2025). "Additionally, ERCC1 is inconsistently expressed with advancing tumor grade (grade 3 > grade 2 > grade 4 > grade 1), whereas ACTL6A shows significant overexpression with the grade of tumor progression (grade 4 > grade 3 > grade 2 > grade 1)." (PMID 40510426, 2025). "Moreover, ACTL6A knockout suppresses tumor growth in both embryonal and alveolar RMS models, promoting the morphological and biochemical differentiation of these tumors." (PMID 40657395, 2025). "As KLF4 mediates tumor-suppressive effects following ACTL6A depletion, we examined whether ectopic KLF4 expression could reproduce these phenotypes in CRC cells." (PMID 40877226, 2025). "In addition, ACTL6A depletion in the CRC PDOs led to a substantial reduction in tumor cell viability." (PMID 40877226, 2025). "We further confirmed that BAP18 recruited ACTL6A (actin like 6A) and PAF1 (polymerase-associated factor 1), along with β-catenin, to the promoter region of target genes to activate the Wnt signaling pathway, leading to tumor proliferation and metastasis." (PMID 40818609, 2025). "Besides, we revealed that circ_0084615 eliminates the ability of miR‐1200 to destroy ACTL6A mRNA, and thereby promoting tumor progression in HCC." (PMID 39502735, 2024). "Then, we further explored the role played ACTL6A in GC tumor progress." (PMID 37443154, 2023). "We then investigated BRG1 and ACTL6A expression in the collected primary tumours by RTqPCR." (PMID 35201472, 2021). "We observe a dramatic reduction in tumor size for ACTL6A knockout tumors." (PMID 34689163, 2021). "Therefore, the current findings add new biological activities to elucidate how ACTL6A promotes tumor growth and migration." (PMID 31649264, 2019). "High ACTL6A expression significantly correlated with increased tumor grade (P < 0.01)." (PMID 29725063, 2018). "Taken together, these results indicated that ACTL6A promoted tumor cell growth in vivo." (PMID 29725063, 2018). "Notably, the abundance of ACTL6A was increased with the advanced tumor grade." (PMID 39502735, 2024). "Similarly, the lncRNA LINC01133 may regulate the activity of tumor suppressor pathways by dysregulating ACTL6A, SMARCD2, SMO, PHC3, and CENPP." (PMID 34925461, 2021). "11,94 By upregulating phosphoglycerate kinase 1 (PGK1), ACTL6A enhances glycolysis triggered by follicle-stimulating hormone (FSH), promoting tumor growth and metastasis." (PMID 40657395, 2025).
tumor (continued). "This study identifies ACTL6A as a pivotal epigenetic regulator of chromatin accessibility and transcriptional repression in CRC through its inhibitory effect on KLF4, a tumor-suppressive TF." (PMID 40877226, 2025). "The overexpressions of ERCC1 and ACTL6A were found to significantly enhance the infiltration of CD8+ T-cells, macrophages, dendritic cells, CD4+ T-cells, and B-cells into HNC tumor cells." (PMID 40510426, 2025). "Although we did not detect LINC00313 over-expression in CCA tissues, the expression levels of ACTL6A, TCF7, WNT5A, AXIN2 and SULF2 were all increased in CCA human tumours (Fig. EV5B)." (PMID 38332153, 2024). "For instance, ACTL6A is upregulated in HCC and promotes migration and invasion in vitro, as well as tumour growth and metastasis in vivo, via activating Notch signalling." (PMID 38332153, 2024). "In conclusion, ACTL6A accelerates GSH synthesis and then reduces ROS levels to support GC tumor growth." (PMID 37443154, 2023). "IHC of Ki-67 in tumor specimens was performed, which showed that co-therapy with K03861 and PTX markedly reduced the Ki-67 staining intensity in ACTL6A overexpressing tumors among these groups." (PMID 33541412, 2021). "To study the role of ACTL6A in TNBC, we performed soft-agar, colony formation, flow cytometry and tumor formation in nude mice." (PMID 33541412, 2021). "ACTL6A has been reported to regulate the activity of many oncogenes, including WWC, SOX2, c-Myc, which all have important roles in promoting tumor progression." (PMID 29725063, 2018). "Thus, we can predict that both ERCC1 and ACTL6A are upregulated in HNC patients, particularly in individuals with advanced stages and tumor grades and mostly in persons aged 40–80 years." (PMID 40510426, 2025). "Sustained expression of ACTL6A in muscle cells hampers differentiation, while silencing ACTL6A in RMS cells increases the expression of muscle markers, inhibits cell proliferation, and suppresses tumor growth." (PMID 40657395, 2025). "After treatment onset, there was a significant reduction in tumor size with IACS-010759 treatment compared to vehicle in ACTL6A-depleted tumors while no change in tumor volume was observed in control tumors." (PMID 40950224, 2025). "Additionally, we detected metabolites of SNU638 xenograft tumor tissues by LC–MS and found that γ-GC and GSH expression was downregulated after ACTL6A expression was knocked down." (PMID 37443154, 2023). "Actin like 6A (ACTL6A) showed higher level in tumors with advanced stage, and it has been recognized for its contribution to tumorigenesis, proliferation and invasion, and it also promotes the repair of DNA damage induced by cisplatin in tumor cells." (PMID 37033959, 2023). "High levels of ACTL6A protein were significantly associated with FIGO stage (p < 0.01) and differentiation grades (p < 0.01), but not with tumor size (p = 0.452), deep stromal invasion (p = 0.146) and patient age (p = 0.061)." (PMID 34395295, 2021). "Based on our model, where high ACTL6A expression reduces p21Cip1, we interpret these results as suggesting that the tumor samples express enough ACTL6A to partially, but not completely suppress, p21Cip1 expression." (PMID 34689163, 2021). "In addition, the amplification of ACTL6A and BRD9 commonly occurred in multiple cancers and may play crucial roles in tumor formation." (PMID 31504061, 2019). "Interestingly, although non-neoplastic samples were largely negative, increased ACTL6A expression was found in higher tumor grade." (PMID 29725063, 2018). "However, ACTL6A expression exhibited no significant relevance with gender, age, tumor size, tumor location, pN status and mismatch repair (MMR) status (all P > 0.05, respectively)." (PMID 30348114, 2018).
tumor (continued). "In addition, although ACTL6A depletion led to a clear reduction in tumor growth in vitro, these findings may not fully recapitulate the complexity of in vivo conditions, where additional regulatory mechanisms and interactions could influence the observed effects." (PMID 40877226, 2025).
ACTL6A also shares sentences with these, for which no sentence is quoted: esophageal cancer (3 papers); bladder cancer (2); head and neck cancer (2); lung adenocarcinoma (2); triple-negative breast carcinoma (2); acute myeloid leukemia (1); adenocarcinoma (1); bone marrow failure (1); brain tumor (1); cervical squamous cell carcinoma (1); epithelioid hemangioma (1); glioblastoma (1); hemangioendothelioma (1); Huntington disease (1); myeloma (1); neuroendocrine carcinoma (1); non-small cell lung carcinoma (1); oral cancer (1); ovarian serous cystadenocarcinoma (1); pleural mesothelioma (1); prostate carcinoma (1); sarcoma (1); skin disorder (1); skin tumour (1); soft tissue sarcoma (1); uveal melanoma (1); vascular tumors (1).